STAT3 (signal transducer and activator of transcription 3)
Diseases named in the same sentence as STAT3 in open-access papers (continued):
Sharing a sentence is not in itself a finding about the gene and the disease.
cancer (continued). "Moreover, BTG2 over‐expression inhibits interleukin‐6 (IL‐6) expression through downregulation in the STAT3 pathway, as well as inhibiting reactive oxygen species (ROS) generation in the JAK2‐STAT3 signalling pathway; thus it has a negative effect on cancer cell growth." (PMID 29656435, 2018). "Given that a STAT3 inhibitor with ROS-promoting activity may be a new strategy for the treatment of solid tumors, we hypothesized that these new hybrids of curcumin with a BTP moiety may inhibit STAT3 activation and lead to ROS accumulation and ultimately induce cancer cell apoptosis." (PMID 28397855, 2017). "Moreover, the miR-141 DEGs were enriched in signal transducer and activator of transcription 3 (STAT3) and JAK/Stat3 signalling, a well-known regulator of stem cells, suggesting that miR-141 may negatively have an impact on (cancer) stem cell signalling in DU145 cells." (PMID 28112170, 2017). "The mechanisms may include cancer stem cells, hypoxia [e.g., Hypoxia-inducible factor 1α; (HIF-1α)], human papillomavirus (HPV), and signal transduction pathways [e.g., the signal transducer and activator of transcription 3 (STAT3), phosphoinositide-3 kinase (PI3K)/Akt]." (PMID 27823965, 2017). "Given that STAT3 is a critical mediator of differentiation, activation, migration, and inflammatory capacity of immune cells and stromal cells that create the microenvironment supporting tumor cell growth, it will not be surprising that miR-204 has multiple functions in cancer development." (PMID 27438705, 2016). "It has been shown that in atypical teratoid/rhabdoid tumors, cisplatin-resistance could result from activation of STAT3/Snail axis and up-regulation of MRP1, a ATP-binding cassette (ABC) drug transporter that is involved in development of multi-drug resistance in different cancers." (PMID 26799670, 2016). "Moreover, IL-6 driven STAT3 signaling induced the formation of a cancer stem-like population from non-stem PCa cells, which could be inhibited by treatment with the small molecule STAT3 inhibitor, Stattic." (PMID 25595909, 2015). "Indeed we found that SDE-genes identified in previous step are related to STAT3 pathways including genes involved in cell cycle progression (Cyclin D1, D2, and c-Myc), cell survival (Bcl-xL, Bcl-2, Mcl-1), angiogenesis (HIF1α, VEGF), cancer inflammation (NF-KB, IL-6)." (PMID 26056083, 2015). "However, the regulation of signal transducer and activator of transcription-1 (STAT-3) was constitutively active and presented a slight down-regulation after the combination of IFN-γ and TNF-α treatment, which is consistent with others results in the cancer cells." (PMID 25811609, 2015). "However, the signaling by which MDSCs activate STAT3 in cancer cells has not been fully elucidated." (PMID 25075523, 2014). "Besides, it would be interesting to further investigate whether or not Stat3 could regulate PTPN13 in other cancer cells." (PMID 24191246, 2013). "Similarly to NFκB, STAT3 has been shown to act as a non-classical oncogene and plays a role in inflammation-associated cancer underlining its importance in a potential role for PMT in cancer." (PMID 24064721, 2013). "However, the STAT3 pathway has been shown to be a potent regulator of the hypoxic pathway and our in vivo data suggests that AZD1480 may circumvent the induction of hypoxia - a known mediator of treatment resistance to multiple cancer therapies." (PMID 23013619, 2012). "In 8 prostate cell lines from Cancer Cell Line Encyclopedia (CCLE), we found that most of the correlations were positive by calculating Pearson's correlation, except PC3 cell line (no STAT3 expression)." (PMID 39917394, 2025). "In contrast to EBV-infected/cancer cells, EBV-uninfected/cancer cells demonstrate a lower abundance ZC3H18, most likely due to the absence of EBNA1 and a STAT3-mediated repressive effect on ZC3H18." (PMID 40354417, 2025).
cancer (continued). "The observed blockade of Akt, STAT3, and ERK phosphorylation is not merely a downstream effect but the functional nexus of TWP’s anti-cancer action." (PMID 41181611, 2025). "Data from our reconstitution experiments expressing recombinant TARS1, STAT3, and JAK in HEK293 cells also suggest that the scaffolding mechanism does not require a cancer-specific cellular context." (PMID 41380973, 2025). "The STAT3 inhibitor TTI‐101, while not yet FDA‐approved, has shown promise in preclinical studies and clinical trials for various cancers." (PMID 40808640, 2025). "Inhibits the growth of cancer cells through the downregulation of PI3K/Akt, STAT3, VEGF, NF-κB, the non-protein sulfhydryl pathway, lactate dehydrogenase, and creatine kinase." (PMID 40429833, 2025). "It has been also reported that NONO contributes to cancer cell growth and confers drug resistance in TNBC by regulating the signal transducer and activator transcription 3 (STAT3)." (PMID 38493226, 2024). "In addition to NF-κB and STAT3, astragaloside IV could regulate the expression of various signal pathways and growth factors, such as VEGF, Nrf2, HIF-1α, P13k-AKT, etc.51, which were closely related to cancer progression, suggesting that astragaloside IV was a promising anticancer drug." (PMID 39085255, 2024). "We did not observe any significant difference in STAT3 expression and less expression of IL6R and IL6ST in cancer samples compared to paired non-neoplastic samples." (PMID 38979413, 2024). "When elevated levels of phosphorylated STAT3 in NFs were eliminated upon TPCA-1 treatment, in our case, MMP1 was not upregulated and the invasiveness of cancer cells was not promoted." (PMID 38320998, 2024). "CK2 promotes cancer cell growth and clonal expansion, sustaining pivotal survival signaling cascades, such as the ones dependent on AKT, NF-κB, STAT3 and others, counteracting apoptosis through a “non-oncogene” addiction mechanism." (PMID 36035991, 2022). "Despite STAT3′s critical contribution to forming a cancer-supportive TME, no drug targeting STAT3 itself has been clinically approved for this purpose until now." (PMID 36429126, 2022). "In contrast, heteronemin—in the absence of estradiol—inhibits the activation of ERK1/2 and STAT3, but can stimulate PKCα phosphorylation in MCF-7 cancer cells." (PMID 35705962, 2022). "The results of our study demonstrate that violacein significantly inhibited the phosphorylation of STAT3, AKT, and ERK1/2 without reducing the total protein levels in Huh7 cancer stem-like cells." (PMID 34639072, 2021). "In addition, IL-6/JAK/STAT3 signaling could induce “pituitary tumor transforming gene 1” (PTTG1) overexpression with subsequent induction of epithelial-mesenchymal transition, increasing the cancer stem cell population in LNCaP androgen-dependent PC cell lines." (PMID 34830209, 2021). "SNHG3 was previously found to exert oncogenic roles in a plethora of cancers: Based on current studies, SNHG3 was involved in TGF-β, NOTCH, JAK2/STAT3 and HGF pathway to promote cancer cell proliferation, invasion and inhibit apoptosis rate." (PMID 33596916, 2021). "To selectively inactivate STAT3, we employed a cell screening model to identify the small molecule, CIB-6, which specifically inhibits STAT3 activation without affecting STAT1/2 and highlight the potential of using IFN in a combination anti-cancer therapy." (PMID 33805945, 2021). "Based on these results, STAT3 would be a reasonable EV protein candidate for HPV-positive HNSCC, if it had not also been detected in the EVs from the non-cancer HOKg cell line, making this protein a less desirable candidate for progression in our studies." (PMID 34359613, 2021). "We previously developed several nonpeptide small molecule STAT3 inhibitors, such as LLL12, which inhibits STAT3 phosphorylation and suppresses the development of cancer." (PMID 33909625, 2021).
cancer (continued). "In vitro, AZD9150 achieved a decrease in STAT3 expression without affecting STAT1 and STAT5 levels in various human cancer cell lines." (PMID 34440253, 2021). "CT induced apoptosis of esophageal EC109 cancer cells by inhibiting p-STAT3 (Tyr705) and p-JAK2 without effect on the expression of the total STAT3 and JAK2 in vitro and in vivo." (PMID 32265690, 2020). "We examined the expression of P-STAT3 and ZEB1 in cancer tissues and noncancerous tissues and found that the expression of ZEB1 in HNSCC tissue was significantly upregulated, while STAT3 was significantly phosphorylated." (PMID 33363013, 2020). "Our laboratory has also demonstrated that chronically elevated IL-6 can increase STAT3 activation and FIS-1 expression in myotubes and skeletal muscle independent of a cancer environment." (PMID 30918582, 2019). "In particular, STAT3 marks the different aggressiveness features of LNCaP and DU145 cancer cells through its canonical and non-canonical activation pathways, respectively." (PMID 31500219, 2019). "While many direct STAT3 inhibitors have not been clinically well explored in HCC, current clinical data in various other cancers suggest their potential benefit in HCC patients." (PMID 31731457, 2019). "This suggests that either EZH2 and STAT3 do not co-localize on chromatin when EZH2 methylates STAT3, or that EZH2 does not coordinate with STAT3 in the brain as it does in cancer cells." (PMID 31891591, 2019). "We have focused extensively on STAT3 and STAT5 and their described roles in cancer progression, however this is not the universal effect among all STATs." (PMID 31684144, 2019). "In STAT3 driven cancers, SOCS3 seems to be the most important negative feedback regulator and mouse models of SOCS3 ablation show strong STAT3 activation." (PMID 31557897, 2019). "Regarding the interplay between the radiosensitivity effect of MSCs on cancer cells and the inhibition of the Stat3 signaling pathway, to our knowledge, no report has demonstrated that MSC-CM inactivates the Stat3 pathway after radiation in MDA-MB-231 cells." (PMID 30297887, 2018). "Inhibition of cholesterol hemostasis and lack of availability in cancer cells following leelamine treatment halts receptor tyrosine kinase signaling and prevents the activation of downstream PI3K/AKT, STAT3 and MAPK signaling cascades." (PMID 28423677, 2017). "Persistent activation of STAT3 contributes to HIF-1α and VEGF expression in cancer cells and other non-ECs." (PMID 28978186, 2017). "REP1 knockdown induces cell growth inhibition in cancer cells, but not normal cells, via downregulation and inactivation of EGFR and STAT3, respectively." (PMID 28230863, 2017). "As in most non-viral cancers, STAT3 is constitutively active in EBV-related B and epithelial cell cancers and in animal models of KSHV-cancers." (PMID 27458446, 2016). "FLLL32 potently and specifically inhibited STAT3 (no inhibition of STAT1) and exhibited growth-repressive activity in cancer cells with constitutively activated STAT3." (PMID 26887043, 2016). "We further detected the expression of some reported stemness-related genes in HCC and CRC stem cells including CTNNB1, HES1, SMAD4, GLI1, STAT3 and BMI122, 23, 24, 25 in the cancer cell lines with or without PS341 treatment." (PMID 26915315, 2016). "Since AZD6244 is not approved for cancer therapy, we then confirmed our observations with the FDA approved MEK selective inhibitor trametinib, which showed similar results of activating STAT3 mainly through Tyr705 phosphorylation." (PMID 25961376, 2015). "Constitutive activation of STAT3 is observed in 72.4% of human HCC and in a wide variety of other cancer types not in normal cells, which represents an attractive molecular target." (PMID 24418169, 2014). "It is no surprise therefore, that inhibition of STAT3 reduces angiogenesis by reducing VEGF expression and therefore VEGF receptor activity in multiple models of cancer." (PMID 24722453, 2014).
cancer (continued). "In cancer cells with high MET activity, inhibition of EGFR activity alone likely is not sufficient to abrogate STAT3 activity." (PMID 24662938, 2014). "The basis for this phenotype is complex, but it appears that the enhanced ability of IL-11, rather than IL-6, to activate STAT3 and STAT1 in absence of SOCS3 promotes inflammation and cancer." (PMID 24600449, 2014). "A major focus of this review is the potential cancer prevention role offered by STAT3 inhibitors or agents, although there are no FDA-approved STAT3 inhibitors available for clinical use to date." (PMID 24743778, 2014). "Taken together, these results demonstrate that EF24 selectively blocks the NF-κB pathway in cancer cells, but does not affect STAT1 or STAT3 activation." (PMID 23940701, 2013). "Although Stat3 is an important angiogenic factor in cancer and has been shown to be a direct transcriptional activator of VEGF, the involvement of Stat3 in VEGF regulation in the RPE has not been shown so far, and cannot be implicated by our data." (PMID 23401656, 2013). "Our collaborators developed a non-peptide small molecule inhibitor of STAT3, LLL12, which has shown promising results in the treatment of several types of cancer." (PMID 21526200, 2011). "Our results suggested that NSC-743380 selectively modulates functions of RNA polymerase II, JNK, and JAK/STAT3 pathways in a subset of cancer cells, because the functionality of those molecules was not affected by NSC-743380 in the resistant cancer cell lines." (PMID 22174819, 2011). "Not all of the cancer cell lines expressed the same STAT3 downstream targets but cyclin D1, Bcl-2, survivin, DNMT1 and TWIST1 were among the most common STAT3 downstream targets expressed and were inhibited by the STAT3 inhibitor, FLLL32." (PMID 20712901, 2010). "In addition, oncostatin M has been shown to induce EMT in tubular epithelial cells through GP130-mediated activation of JAK2/STAT3 pathway, indicating that this pathway may be critical for cytokine and growth factor-mediated responses regulating EMT biology in fibrogenesis and cancer." (PMID 19088723, 2009). "Further, a JAK/Stat3 small molecular inhibitor, JSI-124, induced apoptosis more selectively in HeLa and SiHa cancer cell lines than Ishikawa cell line without elevated levels of Stat3 phosphorylation." (PMID 17311011, 2007). "Our current study uncovers a novel mechanism of STAT3 activation by TARS1, which may operate in cancer as well as noncancer cells." (PMID 41380973, 2025). "The observed significant suppression of STAT3 and HIF-1α mRNA levels in F9 cancer cells (absent in fibroblasts) correlates with the anti-cancer effects of exogenous SELENOV and may represent an important aspect of its therapeutic potential." (PMID 41463386, 2025). "These experiments showed that heterozygous expression of Rnpc3 is sufficient to markedly restrict the growth and proliferation of cancers driven by a variety of pro-proliferative, pro-survival pathways (KRAS/MAPK and STAT3), without any impact on healthy tissues." (PMID 40624356, 2025). "Additionally, S3I‐201 has been shown to inhibit STAT3 activation in a mouse model of anal squamous cancer negative for HPV, suppressing cancer cell growth and reducing their ability to evade immune responses." (PMID 40166646, 2025). "Moreover, STAT3, but not HIF-1α, plays an important role in hypoxia-induced chemoresistance in BC cancer." (PMID 38415469, 2025). "Although several other TFs, such as nuclear liver X receptor α (LXRα) and signal transducer and activator of transcription 3 (STAT3), have been illuminated as the downstream effectors of Tan, no reports showed the involvement of GLI2 in the anti-cancer property of Tan in human tumors." (PMID 38924029, 2024). "Notably, some inflammation-related pathways were up-regulated exclusively by both cancer plasmid models without TAA but not TAA alone, including IL2/STAT5 signaling, IL6/JAK/STAT3 signaling, and interferon alpha response." (PMID 39254423, 2024).
cancer (continued). "STAT3 has also been connected to NONO and has been shown to induce cancer cell chemoresistance." (PMID 38328550, 2024). "Moreover, MDSCs secrete exosome S100A9 that enhances the activity of signal transducer and activator of STAT3/noncanonical nuclear factor-kappaB (NF-κB) signaling and the production of prostaglandin E2 (PEG-E2), promoting cancer cell stemness and survival." (PMID 36810098, 2023). "Genome wide mRNA expression profile on M-MDSCs from three suppressive and four non-suppressive PDAC patients demonstrated an overall cancer-related gene signature including increased TNFα signaling via NF-κB, inflammatory response, IL6 JAK/STAT3 signaling and apoptosis categories." (PMID 37091970, 2023). "The balancing act between pro-survival STAT3 signaling and pro-death STAT1 signaling downstream of cGAS/STING signaling resulting from CIN allows cancer cells to cope when the insult is not too severe, while still allowing cells to induce apoptosis and promote immune clearance when needed." (PMID 37561163, 2023). "It is important to consider that there are other activators of JAK/STAT3 pathway besides IL-6, and only individual nodes of the target, including IL-6 and IL-6R, are targeted by FDA approved agents, not necessarily in the context of cancer." (PMID 38313431, 2023). "However, this rescue of STAT3 phosphorylation by insulin, IGF1 and leptin was no longer detectable when the cancer cells were treated with the cholesterol-depleting agent MβCD." (PMID 37907500, 2023). "Moreover, we unveil a negative crosstalk between ETV7 and STAT3 in the regulation of the TNFRSF1A gene, and this crosstalk highlights the importance of ETV7 in cancer immunity and inflammation." (PMID 37041130, 2023). "Furthermore, tissue microarray analysis uncovered a positive relationship between the expression levels of STAT3 and WTAP in cancer tissues and adjacent non-cancerous tissues." (PMID 37231451, 2023). "However, miR-500a-3p promotes HCC cancer stem cell properties by targeting PTPN11, a negative regulator of the JAK/STAT3 signaling pathway." (PMID 35957898, 2022). "In these normal tissues where there is very little or no activated STAT3, SBT-100 simply passes in and out of these cells; however, in cancer cells where there is hyperexpression of pSTAT3, SBT-100, upon entering these cells, binds to the pSTAT3 with nanomolar affinity and becomes sequestered." (PMID 35886918, 2022). "Moreover, regardless of the regulation of LEPROT in cancer, it maintained a high correlation with the IL6ST/JAK1/2/STAT3 pathway." (PMID 34804118, 2021). "STAT3 and NONO have been shown to facilitate cancer cell growth, invasion, and migration." (PMID 32724453, 2020). "Furthermore, several studies have reported that in human cancers, including NSCLC, the JAK1/STAT3 pathway (which was not examined here) is blocked/inhibited upon TL treatment." (PMID 32733649, 2020). "For instance, Sox2 and Bcl-3 cooperate to maintain stemness of embryonal stem cells, STAT3 can convert non-CSCs to CSCs, AKT is involved in maintaining Sox2-dependent cervical CSC activity and CSCs isolated from ERα-positive cancer show a hyperactive PI3K pathway." (PMID 33228022, 2020). "Regarding upstream signaling, the JNK or JAK2 inhibitor could inhibit STAT-3 activation in RT-R-MDA-MB-231 cells, but not augmented pKAL-induced anti-cancer effects." (PMID 32326231, 2020). "However, a very recent study has shown that VP demonstrate activity against cancer cell lines that is independent of YAP1 and instead dependent on the ability to induce high MW protein oligomers, in particular STAT3 and SQSTM1." (PMID 30263014, 2018).